PLCG1 (phospholipase C gamma 1)
Diseases named in the same sentence as PLCG1 in open-access papers (continued):
Sharing a sentence is not in itself a finding about the gene and the disease.
rhabdomyosarcoma (1 paper, 2021). A rare aggressive malignant mesenchymal neoplasm arising from skeletal muscle. "Moreover, PTPRG could also modulate the activity of FGFR4 in rhabdomyosarcoma, indeed using siRNA against PTPRG in FGF-treated RH30 cell line increases phosphorylation of the receptor FGFR4 and downstream molecule such as PLCG1 (Phospholipase C-gamma 1) compared to the scramble control." (PMID 35071225, 2021).
sarcoma (1 paper, 2021). A usually aggressive malignant neoplasm of the soft tissue or bone. "And the risk score of PLCG1 and TNF could potentially serve as prognosis markers for sarcoma patients, in clinic." (PMID 34904022, 2021). "However, sarcoma patients with high expression of PLCG1 had poor clinical outcomes, suggesting that it is a PRG biomarker that predicts poor prognosis of sarcoma patients." (PMID 34904022, 2021). "In the nomogram model, as the expression levels of PLCG1 increased, the probability of survival of sarcoma patients decreased; thus, PLCG1 gene expression had a negative correlation with patient survival in sarcoma." (PMID 34904022, 2021). "High expression of PLCG1 in our model was correlated with poor patient survival outcomes and was, to a certain extent, a negative regulator of pyroptosis and had a negative correlation with survival of sarcoma patients." (PMID 34904022, 2021).
triple-negative breast carcinoma (1 paper, 2020). An invasive breast carcinoma which is negative for expression of estrogen receptor (ER), progesterone receptor (PR), and human epidermal growth factor receptor 2 (HER2). "NP-G2-044 treatment decreased the phosphorylation of ERK, PLCγ1, and PI3K downstream of EGF stimulation in EGFR-high triple-negative breast cancer cells." (PMID 32824026, 2020).
vitiligo (1 paper, 2023). Generalized well circumscribed patches of leukoderma that are generally distributed over symmetric body locations and is due to autoimmune destruction of melanocytes. "We noted that other genes, such as Lnc-ARRDC3-1, PLCG1, A_33_P3229958, TERM1, and RAB13, showed increased expression, whereas TM4SF19, IFI27, and IL17RB showed decreased expression in T cells from patients with vitiligo compared with the controls." (PMID 37731844, 2023).
Yersinia infection (1 paper, 2025). "However, those with a normal BMI should be cautious to prevent Yersinia infection, since MAP2K1, PLCG1, and MYD88 exhibit mutual exclusivity and are significantly enriched in this pathway." (PMID 40768543, 2025).
tumor (99 papers, 2004 to 2025). "Trisomy in chromosome 20 or 8 was associated with the promotion of tumor survival by regulating PLCgamma 1 (PLCG1) and MYC." (PMID 41030949, 2025). "At the single-cell level, ELOVL2 was expressed in tumor cells, cancer associated fibroblasts (CAFs) and smooth muscle cells (SMCs), while PLCG1 was presented in CD4+ and CD8+ T cells, as expected." (PMID 37483592, 2023). "Elevated expression of PLCG1 was linked with poor survival and tumor progression in lower-grade glioma (LGG) patients." (PMID 36920176, 2023). "For example, non-native combinations of motifs which bind tumor necrosis factor receptor-associated factors (TRAFs) and phospholipase C gamma 1 (PLCγ1) enhanced cytotoxicity and stemness associated with effective tumor killing." (PMID 36480602, 2022). "Conversely, PLCγ1-pY783High was a remarkably strong risk factor (HR, 20.1; 95% CI, 2.2–178.4; P = 0.003) for pre/perimenopausal patients with Luminal-A tumours." (PMID 31362705, 2019). "Using Kaplan-Meier plots, we also examined the distant recurrence rates associated with PLCγ1-pY1253 and PLCγ1-pY783 expression in luminal tumours with patients clustered according to menopausal status." (PMID 31362705, 2019). "Kaplan-Meier plots showed significant association of high tumour expression of PLCγ1, pY1253-PLCγ1 and pY783-PLCγ1 with low DFS rates (P = 0.005, P = 0.019, P = 0.006, respectively)." (PMID 31362705, 2019). "It is possible that tumor incidence depends on the frequency of DSS exposure and is associated with a PLCγ1-stimulated inflammatory response that affects tumor expression." (PMID 29464031, 2018). "These tumours were characterised by increased phosphorylation of several signalling molecules known to associate with erbB2, including Ptpn11, Plcγ1, Cbl and CrkL, as well as its heterodimerisation partner Egfr." (PMID 25200860, 2014). "Elevated PLCG1 expression levels has been linked to tumor advancement and unfavorable prognosis." (PMID 40725119, 2025). "In addition, increasing variant allele frequency (VAF) of recurrent mutations, includingTET2, RHOAG17V, DNMT3A, IDH2R172, and PLCγ1 observed in several models over passage, indicate clonal expansion or tumor cell enrichment in subsequent passages." (PMID 40510016, 2025). "We found that low PLCG1 expression was associated with poor survival outcomes, which may function as a tumor suppressor gene in GBM." (PMID 40761791, 2025). "Taken together, our results demonstrated that higher PLCG1 expression was associated with tumor growth and worse prognosis in IDH wild-type LGGs and PLCG1 could serve as a potential therapeutic target for IDH wild-type LGG patients." (PMID 34697421, 2022). "The putatively activating hotspot mutation in PLCG1 (R707) was observed in one (3%) tumor." (PMID 26440310, 2015). "The tumor harboring a PLCG1 R707Q mutation also harbored a MYC amplification." (PMID 26440310, 2015). "WES of purified, neoplastic T‐cell (CD3+PD1+) demonstrated high concordance with whole tumor biopsies and validated the presence of TET2 and DNMT3A in tumor and non‐lymphoid cells, but other mutations (CD28, RHOAG17V, IDH2R172, PLCG1) in neoplastic cells." (PMID 40510016, 2025). "After the upregulation of the mRNA expression of PLCG1 in the erlotinib‐plus‐AU‐1 group, its inhibitory effects on tumor growth were significantly rescued." (PMID 37863665, 2023). "The prognostic significance of the PLCG1-high subgroup remained in multivariable analyses adjusted for clinicopathological characteristics including sex, age, tumor-, nodal- and metastasis stage (DSS: HR = 1.642, P = 0.022; OS: HR = 1.545, P = 0.014)." (PMID 37651195, 2023).
tumor (continued). "As previously observed in mRNA expression level, CASP4, GPX4, IL18, NLRP1, and IRF1 were upregulated in tumor samples, whereas PLCG1 was downregulated." (PMID 35000541, 2022). "Meanwhile, more in-depth studies are needed to explore the specific signaling pathways of PLCG1 related to the tumor malignant transformation in IDHwt LGGs." (PMID 34697421, 2022). "It is possible that the increased expression of PLCG1 is due to the presence of tumors and that this increase in PLCG1 is intended to negatively regulate tumor growth." (PMID 35677632, 2022). "Three genes (ELANE, NLRP7, and CASP5) were downregulated, whereas seven others (GSDMC, IL1A, NOD2, GZMB, GSDMA, IL1B, and PLCG1) were overrepresented in the tumour group." (PMID 35087586, 2022). "Another enzyme that has been recently identified as a key element for this tumor aggression mechanisms is the PLCγ1." (PMID 35303162, 2022). "Phosphoinositide specific phospholipase Cγ1 (PLCγ1) plays an important role in regulating cell proliferation and migration of tumor 8-10." (PMID 32210730, 2020). "Now that autophagy is a double-edged sword in tumor progression, it is necessary to confirm the effect of PLCγ1 inhibition-driven autophagy on cell proliferation and migration of A549 cells." (PMID 32210730, 2020). "Although the relationship between oestrogen stimulation and PLCγ expression has been explored in depth, recent data have indicate a role for PLCγ1 in the proliferation of ER-positive tumour cells." (PMID 31362705, 2019). "Multivariate analyses of DFS revealed prognostic significance of tumour expression of PLCγ1 (HR, 1.5; 95% CI, 1.0–2.3; P = 0.029), pY1253-PLCγ1 (HR, 1.6; 95% CI, 1.1–2.3; P = 0.024) and tumour grade." (PMID 31362705, 2019). "Immunohistochemical staining analysis demonstrated that more than half of the patients exhibited phosphorylated ZAP70, ITK and PLCγ1 in tumor tissues of AITL patients, suggesting the continuous activation of the TCR signaling in AITL." (PMID 30814910, 2019). "Our data indicate that tumor progression depends on the frequency of DSS exposure, suggesting that inflammation is associated with PLCγ1 activation." (PMID 29464031, 2018). "Only WT mice developed macroscopic tumors (>4 mm) with a higher average tumor load and tumor number than in PLCγ1 conditional knockout mice." (PMID 29464031, 2018). "As one of 13 mammalian PLC isozymes, PLC gamma 1 (PLCγ1) is primarily activated by extracellular stimuli and is involved in tyrosine kinase signaling and the promotion of tumor cell growth and migration." (PMID 29464031, 2018). "As expected, PLCγ1 was strongly expressed in the AOM/DSS tumor model, whereas it was expressed at approximately normal levels in WT mice." (PMID 29464031, 2018). "We detected dividing tumor cells using p-histone H3 immunohistochemistry (IHC) and found higher proliferation rates in tumors from WT mice compared to PLCγ1 conditional knockout mice." (PMID 29464031, 2018). "The proliferation of tumor cells plays a critical role in tumor development; previous studies showed that PLCγ1 is essential for cell proliferation and differentiation." (PMID 29464031, 2018). "Here, we showed that the expression levels of STAT3 phosphorylation were higher in WT mice than PLCγ1 conditional knockout mice, leading to much higher tumor proliferation and inflammatory responses in the WT mice." (PMID 29464031, 2018). "Consistent with hematoxylin and eosin (H&E) staining, the proliferation of tumor cells was much higher in WT mice than in PLCγ1 conditional knockout mice during tumor progression and development." (PMID 29464031, 2018). "Taken together, these results demonstrate that decreased tumor incidence in PLCγ1 conditional knockout mice is due to reduced inflammation." (PMID 29464031, 2018). "The tumor weight was reduced in the group of PLCγ1-transformed BGC-823 cells (*P < 0.05, vs control)." (PMID 26811493, 2016).
tumor (continued). "As angiogenesis is the requirement for tumor metastasis, we detected the effect of PLCγ1 shRNA on the two biomarkers of angiogenesis, VEGF and CD34." (PMID 26811493, 2016). "Inhibiting PLCγ1 has been known to suppress cell proliferation in several types of tumor, including digestive system tumors." (PMID 26811493, 2016). "The tumor volume after subcutaneous injection of PLCγ1-transformed BGC-823 cells for 29 days was suppressed (*P < 0.05, vs control)." (PMID 26811493, 2016). "Tumor cells with low expression of PLCγ1 show stronger hypoxia adaptation and higher proliferation activity, suggesting that elevated PLCγ1 expression may serve as a biomarker for poor NSCLC prognosis." (PMID 40725119, 2025). "Additionally, PLCG1-targeted drugs significantly inhibited tumor growth in IDH wild-type LGG cell lines and in mouse models." (PMID 38670157, 2024). "The PLCG1-mediated signaling pathway also regulated tumor metastasis." (PMID 36920176, 2023). "In this cellular model, the downregulation of PLCγ1 in hypoxia decreased oxidative cancer cell metabolism, prevented the formation of mitochondrial reactive oxygen species, and drove tumor bioenergetics toward glycolysis by preventing Ca2+ entry into the mitochondria." (PMID 37370855, 2023). "PLCγ1 promotes tumor cell proliferation in KRAS-mutant LC cells, suggesting that PLCγ1 is a novel interactor of the EphA2 RTK in LC cells and that the EphA2–PLCγ1 signaling axis could be a promising therapeutic strategy for treating LC." (PMID 37370855, 2023). "However, following the migration of Tem cells into the tumor microenvironment, their activation is suppressed by mediators (phospholipase C gamma 1 [PLCγ1] and signal transducer and activator of transcription 5B [STAT5B])." (PMID 38203692, 2023). "Additionally, PLCγ1 has been implicated in various cancers in a number of studies, and these studies have highlighted the role of PLCγ1 in tumor progression and metastases." (PMID 37371495, 2023). "PLCγ1 plays a crucial role in the proliferation and migration of tumor cells process." (PMID 37370855, 2023). "Furthermore, in the TCGA‐STAD cohort, the PLCG1 expression level was elevated in tumor tissues in contrast to adjacent non‐tumor tissues and was highly correlated with BPTF expression." (PMID 37863665, 2023). "In our IDHwt LGG samples, we showed that decreased PLCG1 expression suppressed tumor proliferation, migration and invasion and promoted apoptosis owing to a disturbance of the essential functions of PLCG1, such as protein secretion, MYC targets, mitotic spindle, the G2/M checkpoint, and E2F targets." (PMID 34697421, 2022). "PLCG1 was highly expressed in tumor tissue, but patients with high expression had better survival." (PMID 35677632, 2022). "In addition, flow cytometric analysis showed that the number of tumor cells arrested in G2 phase increased significantly, suggesting the importance of PLCG1 in the cell cycle and proliferation." (PMID 34697421, 2022). "Intriguingly, at the nucleotide level, the PLCG1 hotspot Ser345 is altered in the three affected tumor samples in two different ways (c.1034C>T vs. c.1034_1035delinsTT), both resulting in the same amino acid exchange (p.Ser345Phe) with known oncogenic properties." (PMID 34771672, 2021). "A combination between targeting PLCγ1 and autophagy pathway in anti-tumor therapy may be an efficacious new strategy to overcome the autophagy addition of tumor and acquired resistance to current therapy." (PMID 32210730, 2020). "Additionally, the effect of shRNA/PLCγ1 alone or combined with autophagic activator Lithium Chloride (LiCl) on tumor growth and metastasis was measured using immunohistochemistry and assays in A549 xenograft nude mouse model." (PMID 32210730, 2020).
tumor (continued). "It highlights the potential role of a combination between targeting PLCγ1 and autophagy pathway in anti-tumor therapy, which may be an efficacious new strategy to overcome the autophagy addition of tumor and acquired resistance to current therapy." (PMID 32210730, 2020). "Furthermore, the effect of shRNA/PLCγ1 alone and combination with autophagy activator Lithium Chloride (LiCl) on tumor growth and metastasis was evaluated in A549 xenograft nude mouse model." (PMID 32210730, 2020). "Red and grey lines represent tumours expressing high and low PLCG1 mRNA levels, respectively." (PMID 31362705, 2019). "Red and black lines represent tumours expressing high and low PLCG1 mRNA levels, respectively." (PMID 31362705, 2019). "Phospholipase Cγ1 (PLCγ1) is highly expressed in human tumours." (PMID 31362705, 2019). "Similarly for tumour expression of PLCγ1-pY1253High and PLCγ1-pY783High, as 173/414 (41.8%) and 87/414 (21.0%), respectively." (PMID 31362705, 2019). "In all, 189 of 414 (45.7%) patients showed high tumour PLCγ1 expression levels (PLCγ1High)." (PMID 31362705, 2019). "In our series, the prognostic value of PLCγ1 overexpression was restricted to Luminal type tumours." (PMID 31362705, 2019). "PLCG1 is generally activated by growth factor receptors such as vascular endothelial growth factor receptors (VEGFRs), insulin-like growth factor 1 receptor (IGF-1R) and FGFRs and has been linked to metastatic tumour progression." (PMID 29188362, 2018). "Recurrent PTPRB and PLCG1 mutations have been previously reported in this tumor type; however, no somatic coding mutations affecting either gene were found in our data set." (PMID 28056866, 2017). "On the other hand, the depletion of PLCγ1 by shRNA3 led to the decrease in CD34 (one of biomarkers of vascular density) and VEGF protein levels, and VEGF mRNA level in tumor tissue, indicating the involvement of PLCγ1 in the angiogenesis of tumor (*P < 0.05, ****P < 0.0001, vs control)." (PMID 26811493, 2016). "It is also reported that PLCγ1 promotes the invasion of several types of tumor." (PMID 26096802, 2015). "Thus, the data indicated that the levels of PKCδ and CaMK IIβ were down-regulated in the depletion of PLCγ1 by shRNA-mediated tumor growth and metastasis suppression." (PMID 26633375, 2015). "PLCG1 is a member of the phosphatidylinositol-specific phospholipase C (PLC) family that hydrolyzes phosphatidylinositol 4,5-bisphosphate (PIP2) to generate inositol 1,4,5-trisphosphate and diacylglycerol (DAG), which is associated with the proliferation and invasion of tumor cells." (PMID 36386841, 2022). "However, the relationships between PLCG1-mediated pyroptosis and tumour development remain largely unknown." (PMID 33828074, 2021). "However, the correlation between PLCG1-mediated pyroptosis and tumour development remains largely unknown." (PMID 34904022, 2021). "Additionally, the abrogation of PLCγ1 signaling by shRNA and combination with autophagic activator LiCl could efficaciously suppress tumor growth and metastasis in A549 xenograft nude mice, in combination with a decrease in P62 level." (PMID 32210730, 2020). "Hence, there exists a link between PLCγ1 and autophagy in tumor progression." (PMID 32210730, 2020). "In this way, PLCγ1 plays a crucial role in fostering the growth and metastasis of some tumor types through interaction with other signal molecules, and may be a useful target for anti-tumor therapy." (PMID 26811493, 2016). "In this respect our present data, together with our previous work indicating the critical role of PLCγ1 in metastasis development and progression suggest that targeting PLCγ1 may represent a useful strategy to inhibit metastasis growth and possibly tumour angiogenesis simultaneously." (PMID 20011604, 2009). "Activation of PLCγ1 induced by VEGF is also involved in regulating endothelial cell proliferation and tumor angiogenesis and growth." (PMID 37298555, 2023).